SLC2A5 (solute carrier family 2 member 5)
Diseases named in the same sentence as SLC2A5 in open-access papers (continued):
Sharing a sentence is not in itself a finding about the gene and the disease.
metastatic cancer (1 paper, 2022). A carcinoma which has spread from the original site of growth to another anatomic site. "Metastasis is the primary cause of cancer patient death and the elevation of SLC2A5 gene expression is often observed in metastatic cancer cells." (PMID 36268513, 2022).
cancer (66 papers, 2011 to 2025). A tumor composed of atypical neoplastic, often pleomorphic cells that invade other tissues. "Overexpression of SLC2A5, and hence GLUT5, is associated with enhanced tumourigenesis, migration, and invasion, all of which contribute to cancer metastasis." (PMID 39199548, 2024). "The high or specific expression of other glucose transporters such as GLUT2/SLC2A2, GLUT3/SLC2A3, GLUT12/SLC2A12 and the fructose transporter GLUT5/SLC2A5 has also been associated with various cancer types and specific cancer stages." (PMID 36770817, 2023). "The direct association of increased abundance of SLC2A5 in cancer cells with metastatic risk in several types of cancers identifies SLC2A5 as an important therapeutic target to reduce or prevent cancer metastasis." (PMID 36268513, 2022). "Based on our findings, inhibition of SLC2A5 is a useful strategy for reducing the risk of metastasis, a deadly aspect of human cancers." (PMID 36268513, 2022). "The gene encoding SLC2A5, a fructose-specific transporter, is highly expressed in cancers whereas it is tightly regulated in healthy tissues." (PMID 36268513, 2022). "Specifically, increased abundance of both SLC2A5 mRNA and protein have been associated with cancer progression and increased frequency of metastasis of many cancers." (PMID 36268513, 2022). "In SLC2A5-deficient cancer cells, mitochondria became elongated, increased in number, and dispersed throughout the cell, which prevented efficient cellular extravasation." (PMID 36268513, 2022). "Despite substantial evidence indicating that SLC2A5 is associated with multiple cancers, the mechanism of SLC2A5 in cancer remains elusive." (PMID 34188196, 2021). "SLC2A5 is a fructose transporter and has been reported to be associated with various cancers as well 62-64." (PMID 33391440, 2021). "Moreover, attenuation of SLC2A5 function caused a reduction in the number of mitochondria, alteration of their morphology as well as their localization in cancer cells, underscoring the importance of mitochondrial function in cell motility." (PMID 36268513, 2022). "Notably, increased abundance of SLC2A5 mRNA and protein in cancer cells is associated with cancer progression, increased frequency of metastasis, and an unfavorable prognosis for many cancers." (PMID 36268513, 2022). "In terms of overall survival, only adenocarcinoma is significantly associated with the expression levels of SLC2A5, implying that metabolism of cancer cell is complicated and its dependency on a specific nutrient is likely influenced by cell origin and oncogenic drivers." (PMID 29531835, 2018). "Also, the loss of SLC2A5 has been shown to inhibit cancer cell migration." (PMID 38971308, 2024). "These cells often express high levels of the fructose transporter SLC2A5/GLUT5, allowing them to take up more fructose from the surrounding environment and promoting cancer growth." (PMID 39406918, 2024). "We used three animal models to evaluate the importance of SLC2A5 in cancer metastasis in vivo: the chicken embryo chorioallantoic membrane (CAM), xenograft murine model and the zebrafish." (PMID 36268513, 2022). "We found that CRISPR/Cas9-mediated inactivation of the SLC2A5 gene reduced cancer cell proliferation and inhibited motility in a variety of cancer cell lines." (PMID 36268513, 2022). "Fructose interacts with the GLUT5 (also known as SLC2A5) glucose transporter receptor (a type of lectin receptor) and thus helps in targeting these receptors predominantly expressed by cancer cells." (PMID 36364286, 2022). "This indicates that SLC2A5 function is required for mitochondrial polarization towards the cell protrusions and directional migration of cancer cells." (PMID 36268513, 2022). "We also unexpectedly discovered that the localization and structure of mitochondria in cancer cells with attenuated SLC2A5 function contribute a role in the metastatic potential of cancer cells." (PMID 36268513, 2022).
cancer (continued). "We discovered that CRISPR/Cas9-mediated inactivation of the SLC2A5 gene inhibited cancer cell proliferation and migration in vitro as well as metastases in vivo in several animal models." (PMID 36268513, 2022). "Specifically, the attenuation of the SLC2A5 gene expression inhibited cancer cell invasion and metastasis in vivo as we demonstrated in chick embryo, mouse, and zebrafish models." (PMID 36268513, 2022). "In this study, we assessed the importance of the SLC2A5 gene on cancer cell proliferation, migration, extravasation, and colony formation." (PMID 36268513, 2022). "Taken together, our data showed that SLC2A5 function is necessary for polarization of mitochondrial distribution and directional cancer cell migration, which impact on cancer cell motility and extravasation." (PMID 36268513, 2022). "SLC2A5 is a high-affinity fructose transporter, which is frequently upregulated in multiple human malignant tumours." (PMID 34188196, 2021). "To study the role of GLUT5-mediated fructose utilization in cancer cell survival, we depleted SLC2A5 expression by shRNAs." (PMID 29531835, 2018). "Pharmacological inhibitors of SLC2A5 have been shown to be effective in a variety of cancers." (PMID 40362545, 2025). "Hypoxic conditions promoted SLC2A5 expression, fructose uptake, and cancer cell survival." (PMID 40362545, 2025). "Furthermore, a positive correlation was found between SLC2A5 and IL-6 expression in a variety of cancers." (PMID 40362545, 2025). "Furthermore, we discovered that suppression of the SLC2A5 gene in cancer cells resulted in notable changes in mitochondrial architecture and distribution, which substantially altered cell migration." (PMID 36268513, 2022). "Reduced SLC2A5 function alters distribution and morphology of mitochondria in cancer cells." (PMID 36268513, 2022). "Here we show that silencing of the SLC2A5 fructose transporter by gene editing in cancer cells inhibited cell motility and proliferation in vitro as well as inhibited cancer cell invasion and metastasis in chicken embryo, mouse, and zebrafish models of human cancer progression." (PMID 36268513, 2022). "Here we evaluated the importance of SLC2A5 in cancer cell motility by silencing its gene." (PMID 36268513, 2022). "Attenuation of SLC2A5 function inhibits cancer cell migration." (PMID 36268513, 2022). "To test whether fructose binding/transport activity is involved in the enhanced motility of cancer cells, we introduced the E401A mutant of the human SLC2A5 into SLC2A5 gene-edited MIA-PaCa-2 or HT1080tdT cells." (PMID 36268513, 2022). "Moreover, SLC2A5-attenuated cancer cells exhibited dramatic alterations in mitochondrial architecture and localization, uncovering the importance of SLC2A5 in directing mitochondrial function for cancer cell motility and migration." (PMID 36268513, 2022). "To determine how broadly this adaptation extends, we screened the GLUT5 protein coding gene, SLC2A5, in datasets registered in the Genomics of Drug Sensitivity in Cancer (GDSC), Cancer Genome Atlas (TCGA) and the Genotype-Tissue Expression (GTEx) Portal." (PMID 38766088, 2024). "Cancer cells express solute carrier family member 5 (SLC2A5), the fructose transporter, and upregulation of SLC2A5 is indicative of a poor prognosis for cancer patients that experienced an increase in cancer cell proliferation, colony growth, and metastasis." (PMID 39529665, 2024). "Overexpression of SLC2A5 enhances LUAD cellproliferation, migration, invasion, and tumorigenicity in fructose-containing culturemedium, and cancer cells are more sensitive to paclitaxel treatment after inhibition ofGLUT5 with 2,5-AM." (PMID 37674366, 2023). "In conclusion, we demonstrated that limiting the function of the SLC2A5 (GLUT5) fructose transporter inhibited cell proliferation, motility and cancer cell metastasis." (PMID 36268513, 2022).
cancer (continued). "Next, Dr Jody Groenendyk (University of Alberta, Edmonton, Canada) pursued the discussion on cancer metabolism and presented data on fructose, one of the main sources of energy of cancer cells, transported by the SLC2A5 (GLUT5) transporter, often upregulated in cancer." (PMID 37409695, 2023). "Our results reveal that neither the known cancer driver genes nor the extracellular fructose level is efficient to influent SLC2A5 expression in LUAD." (PMID 29748554, 2018). "However, attenuation of the SLC2A5 gene expression had no apparent influence on cancer cell migration velocity." (PMID 36268513, 2022).
tumor (42 papers, 2012 to 2025). "Some tumor cells upregulate the transcription of the GLUT5-encoding gene SLC2A5 to increase fructose utilization." (PMID 40549205, 2025). "Meanwhile, glucose transporter 5 (Glut5, encoded by SLC2A5), a specific transporter of fructose, was found to be upregulated in these tumor cells, and its expression level was closely correlated with malignant evolution and clinical prognosis." (PMID 37507736, 2023). "Results of our study found that SLC2A5 is highly expressed in LUAD tumor tissues and is also significantly associated with its prognosis." (PMID 34604392, 2021). "This may indicate that changes in SLC2A5 levels are associated with inflammation, viruses, flora changes, infection, etc., thus affecting tumor occurrence and/or progression." (PMID 34604392, 2021). "Under different culture conditions, inhibiting SLC2A5 (GLUT5) can affect the activity and proliferation of specific tumor cells." (PMID 41425581, 2025). "An SLC2A5 inhibitor was hsown to have effectively inhibited fructose-induced tumor angiogenesis and suppresses tumor growth in mice." (PMID 40549205, 2025). "Similar results were observed in tumor tissues derived from U87 cells with disruption of ATF4 binding motifs in the promoters of SLC2A5 or ALDOB." (PMID 36245009, 2022). "The differential expression of SLC2A5 in various tissues from Oncomine, GEPIA, and other databases was obtained, and SLC2A5 expression at the protein level in normal and tumor tissues was detected with the use of the HPA database." (PMID 34604392, 2021). "The Slc2a family, consisting of the genes Slc2a3, Slc2a4, Slc2a5, Slc2a6 and Slc2a7, is responsible for glucose transporters, and exhibited increased transcription in WT type mice tumor compared to KO tumor." (PMID 34685767, 2021). "Oncomine and TIMER databases were used to evaluate the mRNA expression of SLC2A5 in multiple tumor tissues and normal tissues." (PMID 34604392, 2021). "Meanwhile, the Human Protein Atlas (HPA) database was used to detect SLC2A5 expression in normal and tumor tissues." (PMID 34604392, 2021). "At the same time, UALCAN analysis showed that there was statistical difference between SLC2A5 expression and each tumor stage (P < 0.05)." (PMID 34604392, 2021). "On another, analysis in UALCAN examined the protein expression of SLC2A5 and found it was highly expressed in tumor tissues." (PMID 34604392, 2021). "To evaluate the in vivo effects of SLC2A5 on tumour metastasis, we constructed intrasplenic inoculation model in mice." (PMID 34188196, 2021). "Studies have found that the expression of SLC2A5 is closely related to the metabolism of tumor cells and tumor progression, especially the increase of SLC2A5 coding GLUT5 protein seems to be associated with the development and metastasis of LUAD." (PMID 34604392, 2021). "In HCC, tumor endothelial cells enhanced fructose metabolism by upregulating SLC2A5 and KHK, thereby activating the AMPK signaling pathway and mitochondrial function, enhancing endothelial cell function, and exacerbating tumor angiogenesis, growth, and metastasis." (PMID 40520908, 2025). "SLC2A5 promotes tumor cell metabolism and proliferation by increasing fructose uptake." (PMID 41425581, 2025). "Herein, we further investigated the association between glycolysis and IDO1 in PC with bioinformatic analysis and found the expression of SLC2A1, SLC2A3, SLC2A5 (encoding GLUT1, GLUT3, GLUT5 protein), and IDO1 in the tumor tissues of PC patients was increased compared to the adjacent normal tissues." (PMID 38706741, 2024). "Additionally, lower levels of SLC2A3, SLC2A6, SLC2A9, SLC2A12, and SLC2A14 and higher levels of SLC2A1, SLC2A5, SLC2A10, and SLC2A11 had an association with advanced tumor stage." (PMID 36518662, 2022). "In addition, we also found that in the normal intestinal mucosal gland cells, SLC2A5 was mainly expressed on the cell membrane, while in the tumour cells, SLC2A5 was expressed both on the cell membrane and in the cytoplasm." (PMID 34188196, 2021).
tumor (continued). "Reverse SLC2A5 overexpression in LADC tissues may have the biological function of inhibiting tumor metastasis of LADC, providing a possible option for the treatment of LADC." (PMID 32903414, 2020). "BTBD7-SLC2A5 may be involved in unregulated cell adhesion, motility and epithelial morphogenesis due to loss of exons 10 and 11 of BTBD7, or be involved in shifting of energy metabolism to enhance tumor growth due to containing entire transmembrane domain and fructose transport domain of SLC2A5." (PMID 33391440, 2021). "Significant overexpression of SLC2A1, SLC2A5, and SLC2A11 across various tumor types, including LUAD." (PMID 40824962, 2025). "LUAD tumor tissues showed higher mRNA expressions of SLC2A1, SLC2A5, and SLC2A12 and lower expressions of SLC2A3, SLC2A4, SLC2A6, SLC2A9, and SLC2A14." (PMID 36518662, 2022). "According to data from the UALCAN database, LUAD patients’ tumor tissues had hypomethylation of SLC2A1, SLC2A2, SLC2A5, SLC2A6, SLC2A7, SLC2A11 and hypermethylation of SLC2A3, SLC2A10, and SLC2A14 compared to normal tissues." (PMID 36518662, 2022). "A lower differentiation grade tumor is implied by overexpression of SLC2A1, SLC2A5, SLC2A10, SLC2A11and lower levels of SLC2A3, SLC2A6, SLC2A9, SLC2A12, and SLC2A14, emphasizing the possibility of these molecular roles for predicting the course of the tumor." (PMID 36518662, 2022). "In conclusion, this analysis provides a detailed description of the relationship between SLC2A5 and immune characteristics in LUAD patients, indicating that SLC2A5 is a key factor of immune escape in the tumor microenvironment." (PMID 34604392, 2021). "SLC2A5, namely, fructose transporter GLUT5 gene, is one of the key genes in the process of tumor development, whose regulation mechanism is the regulation of fructose uptake and absorption and carbon absorption in cells." (PMID 34604392, 2021). "We identified 15, 12, 15, and 12 reads from tumor samples 306, 409, 206 and 815, in which at least 25 nts mapped in the genes for both BTBD7 and SLC2A5." (PMID 33391440, 2021). "To explore the expression of SLC2A5 in CRC patients, we performed qRT-PCR and western blotting analysis and found that mRNA and protein levels of SLC2A5 were significantly increased in tumours compared to paired normal tissues." (PMID 34188196, 2021). "Here, we evaluated the expression levels of SLC2A5 in CRC tissues and cell lines, and further elucidated the role and molecular mechanism of SLC2A5 in promoting tumour metastasis." (PMID 34188196, 2021). "Moreover, each tumor stage also has high expression, at the same time, the correlation between SLC2A5 expression and prognosis based on different clinical characteristics indicates that SLC2A5 may be a potential independent biomarker for LUAD prognosis." (PMID 34604392, 2021). "To further validate the protein expression of SLC2A5 in CRC patients, we performed IHC analysis on 25 pairs of tumour and adjacent normal tissues." (PMID 34188196, 2021). "SLC2A1, SLC2A5, SLC2A10, and SLC2A11 levels tended to be higher in patients with advanced tumor stages, which shows that these molecules may be involved in the development of malignancies in LUAD patients." (PMID 36518662, 2022). "In our study, we show that transcriptional levels of SLC2A1, SLC2A5 are upregulated and those of SLC2A3, SLC2A6, SLC2A9, SLC2A14 are downregulated in LUAD patients, supporting the role of SLC2A1, SLC2A5 as oncogenes and SLC2A3, SLC2A6, SLC2A9, SLC2A14 as tumor suppressor genes." (PMID 36518662, 2022). "Finally, we used the LinkedOmics database to evaluate the SLC2A5-related coexpression and functional network of SLC2A5 in LUAD and to investigate their role in tumor immunity." (PMID 34604392, 2021). "The results showed that strong SLC2A5 signal was found in almost 75% tumour tissues, while almost all adjacent normal tissues showed weak or absent SLC2A5 expression." (PMID 34188196, 2021).
tumor (continued). "Finally, we used the LinkedOmics database to evaluate the SLC2A5-related coexpression and functional networks in LUAD and to investigate their role in tumor immunity." (PMID 34604392, 2021). "And the distribution of SLC2A5 increased in all stages of tumor; however, the expression of SLC2A5 did not increase with the increase of tumor stage, that is to say, there was no linear relationship between the expression of SLC2A5 and tumor stage." (PMID 34604392, 2021). "Nude mice xenograft tumor experiments further confirmed that reducing lnc-REG3G-3-1 can inhibit the tumor growth by inducing increased miR-215-3p and decreasing the expression of leptin and SLC2A5 in vivo." (PMID 32903414, 2020).
metabolic disease (11 papers, 2017 to 2024). A congenital disorder (due to inherited enzyme abnormality) or acquired (due to failure of a metabolically important organ) disorder resulting from an abnormal metabolic process. "In prior studies, modulation of fructose transporter GLUT5 (SLC2A5) was found to have potential for treating metabolic disease, since GLUT5 is involved in fructose metabolism and intestinal fructose absorption." (PMID 35806147, 2022).
infection (7 papers, 2015 to 2025). The state of being infected such as from the introduction of a foreign agent such as serum, vaccine, antigenic substance or organism. "The downregulated lncRNA A230001M10Rik is strongly correlated with Fabp7, Slc2a5, and Depdc7, which might suggest potential roles in neural homeostasis, glial metabolism, and cellular proliferation during infection." (PMID 41214723, 2025). "Previous studies have found increases in the expression of indoleamine 2,3-dioxygenase 1 (IDO1) associated with intestinal flora and the differentiation of gut secretion cells is related to inflammation, injury, infection, changes in flora, and so on, but with reduced SLC2A5 levels." (PMID 34604392, 2021). "In addition to immunity, genes associated with metabolism (e.g. SLC5A6, SLC2A5, UGT2A3, and PDE6C) as well as membrane proteins, like TM4SF4, were also detected with a significantly higher expression level in CE infection sheep at four hour post infection, when compared with healthy controls." (PMID 26252489, 2015).
SLC2A5 also shares sentences with these, for which no sentence is quoted: Hypertension (5 papers); Insulin resistance (5); prostate carcinoma (5); glioblastoma (4); Hepatic steatosis (4); breast adenocarcinoma (3); cholangiocarcinoma (3); triple-negative breast carcinoma (3); adenocarcinoma (2); breast (2); clear cell renal cell carcinoma (2); hyperglycaemia (2); renal cell carcinoma (2); squamous cell carcinoma (2); thyroid cancer (2); Anxiety (1); aortic stenosis (1); blood cancer (1); brain cancer (1); breast invasive ductal carcinoma (1); breast tumor (1); cataract (1); cervical cancer (1); coeliac disease (1); depression (1); digestive system diseases (1); endometrial cancer (1); eye cancer (1); fibrosis (1); follicular thyroid cancer (1).
A further 37 diseases each share a sentence with SLC2A5 in 1 paper.